CSAG2 (CSAG family member 2)
Description:
Drug-resistance related protein, its expression is associated with the chemotherapy resistant and neoplastic phenotype. May also be linked to the malignant phenotype.
Synonyms: CT24.2; TRAG-3; TRAG3; CSAG3B
Gene: Protein-coding gene on chromosome X (152,708,261 to 152,721,661, reverse strand). Ensembl gene ENSG00000268902.
Homologues: Paralogues in human: CSAG3 (99% identical), CSAG1 (52% identical).
Diseases named in the same sentence as CSAG2 in open-access papers:
CSAG2 is named in the same sentence as 7 diseases in open-access papers, as found by Europe PMC text mining. Sharing a sentence is not in itself a finding about the gene and the disease. The quoted sentences say what the papers report.
breast carcinoma (1 paper, 2011). "Consistent with this notion, we recently found significantly higher frequency of CT mRNA expression in estrogen receptor (ER) and progesterone receptor (PR) negative breast cancer cell lines and primary breast cancers, including MAGE-A3, MAGE-A6, NY-ESO-1, MAGE-A12, LAGE-1, CSAG2 etc." (PMID 21437249, 2011).
ovarian carcinoma (1 paper, 2020). A malignant neoplasm originating from the surface ovarian epithelium. "Although CSAG2 has been associated with paclitaxel resistance in ovarian cancer in vitro and in clinic study, its specific functions remain elusive and contradictory." (PMID 33519462, 2020). "CSAG2, also known as taxol (paclitaxel)-resistance-associated gene-3 (TRAG-3), is overexpressed in paclitaxel-resistant ovarian cancer cells, and also shown to be negatively associated with clinical outcome after paclitaxel treatment." (PMID 33519462, 2020). "By using RIP assay, followed by validation, we demonstrate that the mRNA of CSAG2, one protein closely related to paclitaxel resistance in ovarian cancer, binds with CEPB4." (PMID 33519462, 2020). "In this study, we report that CPEB4 promotes paclitaxel resistance in ovarian cancer, and suggest that this effect depends on its translational regulation of CSAG2." (PMID 33519462, 2020). "Elucidating these issues would not only help us to deeply understand paclitaxel resistance in ovarian cancer, but also develop a rational therapeutic treatment targeting active CEPB4/CSAG2 axis in paclitaxel-resistant ovarian cancer." (PMID 33519462, 2020). "We speculate this regulatory circuit may be one of the mechanisms through which CSAG2 promotes paclitaxel resistance in ovarian cancer." (PMID 33519462, 2020). "Another critical issue needs to be addressed is whether CPEB4-regulated paclitaxel resistance via CSAG2 in ovarian cancer can be reproduced with in vivo scenarios." (PMID 33519462, 2020). "We then asked whether CSAG2 mediates the promotive effect of CPEB4 on paclitaxel resistance in ovarian cancer cells." (PMID 33519462, 2020). "Moreover, CSAG2 expression is upregulated in paclitaxel-resistant ovarian carcinoma and cancer cell lines, and more importantly, siRNA-mediated CSAG2 knockdown overtly attenuates CPEB4-mediated paclitaxel resistance." (PMID 33519462, 2020). "Thus, interfering CPEB4/CSAG2 axis might be of benefit to overcome paclitaxel-resistant ovarian cancer." (PMID 33519462, 2020). "Deduced from our findings, it is possible that ovarian cancer cells may develop paclitaxel resistance through upregulating CEPB4 and thereafter inducing translational expression of CSAG2." (PMID 33519462, 2020). "Consistently, similar tendency was obtained when examining the effect of CSAG2 knockdown on CPEB4-mediated advantages for colony formation, further strengthening the notion that CSAG2 at least in part contributes to CPEB4-mediated paclitaxel resistance in ovarian cancer." (PMID 33519462, 2020).
pancreatic ductal adenocarcinoma (1 paper, 2020). An infiltrating adenocarcinoma that arises from the epithelial cells of the pancreas. "Moreover, in a genome-wide screening study, CSAG2 was found to be coimmunoprecipitated with CPEB4 in pancreatic ductal adenocarcinoma cells line, although remains to be validated further." (PMID 33519462, 2020).
prostate carcinoma (1 paper, 2016). A carcinoma that arises from epithelial cells of the prostate gland. "We observed that CSAG2, even though previously reported to be highly expressed in prostate cancer, was generally higher in our BPH as compared with PCa sera." (PMID 26885621, 2016).
cancer (3 papers, 2019 to 2024). A tumor composed of atypical neoplastic, often pleomorphic cells that invade other tissues. "Furthermore, resistance to paclitaxel in cancer cells occurs through the activation of efflux drug proteins, modification of molecular pathways involved in apoptosis, and upregulation of paclitaxel resistance-associated gene-3 (TRAG-3/CSAG2) expression." (PMID 39003454, 2024). "Examples of biclusters from this category include the biclusters consisting of genes from the Cancer-Testis antigens family—MAGEA2, MAGEA3, MAGEA6, MAGEA10, CSAG1, CSAG2, CSAG3 (Xq28)/CT45A3, CT45A5, CT45A6 (Xq26.3)." (PMID 31216036, 2019).
CSAG2 also shares sentences with these, for which no sentence is quoted: melanoma (1 paper); Ovarian Tumors (1).